ADA (adenosine deaminase)
Diseases named in the same sentence as ADA in open-access papers (continued):
Sharing a sentence is not in itself a finding about the gene and the disease.
atherosclerosis (7 papers, 2018 to 2024). A disease characterized by the build-up of fatty material and calcium deposition in the arterial wall resulting in partial or complete occlusion of the arterial lumen. "Overactivity of serum ADA has been described in patients with increased cardiometabolic risk and atherosclerosis." (PMID 33053898, 2020). "The increase in serum ADA activity was also more pronounced in males than in females, reflecting a greater susceptibility of men to the development of atherosclerosis." (PMID 33053898, 2020). "ADA is involved in the atherosclerosis process, and HDL-C acts as a protective factor in atherosclerosis." (PMID 36260871, 2022). "Another substantial role of ADA in the modulation of immune response that leads to atherosclerosis is differentiation of monocytes to macrophages with subsequent macrophage proliferation dependent on Th cells." (PMID 33053898, 2020). "Therefore, increased vascular ADA activity has been proposed as an early marker and trigger of atherosclerosis." (PMID 36260871, 2022). "Increasing ADA concentrations have been reported to precede macrophage accumulation of macrophages and vascular lipid deposition, and then increased with higher plaque formation in a mouse model of atherosclerosis." (PMID 36260871, 2022). "Dysregulated ADA activity leads to cardiovascular pathologies such as atherosclerosis, thrombosis, and myocardial ischemia-reperfusion injury, suggesting that ADA may be a critical target for treatment of cardiovascular disease." (PMID 36467085, 2022). "Moreover, using a mouse model of atherosclerosis, we established that the increase in vascular eADA activity was much higher comparing to ADA activity in serum." (PMID 33053898, 2020). "Another mechanism that can contribute to the development of atherosclerosis is that high levels of ADA can increase the release of reactive oxygen species from neutrophils, through a downregulation of the inhibitory adenosine/cAMP system and an enhanced activation of A1 receptors." (PMID 30159340, 2018).
brucellosis (7 papers, 2012 to 2024). Brucellosis is a bacterial infection that spreads from animals to people via unpasteurized dairy products or by exposure to contaminated animal products or infected animals. "Infections and conditions like legionella, brucellosis, and Behcet’s disease can cause high ADA levels." (PMID 39641275, 2024).
Fanconi anemia (7 papers, 2013 to 2025). Fanconi anemia (FA) is a hereditary DNA repair disorder characterized by progressive pancytopenia with bone marrow failure, variable congenital malformations and predisposition to develop hematological or solid tumors. "HSC-based gene therapy is gaining traction with a number of clinical trials targeting different conditions (X-SCID, ADA-SCID, ALD, CGD, Fanconi anemia, β-thalassemia) showing encouraging results and which have implications for curative lifelong treatment." (PMID 25118036, 2014).
HIV-1 infection (7 papers, 2011 to 2024). The type species of lentivirus and the etiologic agent of acquired immunodeficiency syndrome (AIDS). "As expected from previous data, HIV-1 infection of MF with either ADA or NLAD8 strains triggered efficient MF fusion into MGC compared to non-infected cells." (PMID 32365752, 2020). "The use of CCR5-displaying peptidoliposomes alone was ineffective at inhibiting R5-JRFL or ADA HIV-1 infection." (PMID 26629902, 2015). "Therefore, inclusion of surface ADA expression analysis in the assessment of immune status during chronic HIV-1 infection may provide a new, biologically meaningful clinical metric, particularly with respect to its role in enhancing telomerase activity." (PMID 23717651, 2013). "For an overview of the effects of TLR-ligation on HIV-1 infection of MDM, cells from two different donors were treated with LPS, a TLR4 ligand, at the time of infection by ADA and either washed out with virus or replaced after washing and maintained during one week culture." (PMID 21904615, 2011). "Our results suggest that ADA, LRRN3 and telomerase activity in CD8+ T cells may serve as novel, clinically relevant biomarkers of immune status in HIV-1 infection, specifically by demonstrating the degree to which CD8+ T cells have progressed to the end stage of replicative senescence." (PMID 23717651, 2013).
Omenn syndrome (7 papers, 2012 to 2025). An inflammatory condition characterized by erythroderma, desquamation, alopecia, chronic diarrhea, failure to thrive, lymphadenopathy, and hepatosplenomegaly, associated with severe combined immunodeficiency (SCID). "This is the first report, to the best of our knowledge, of an atypical Omenn syndrome due to ADA deficiency with expansion of CD56brCD16− NK cells." (PMID 25954555, 2012). "We present here a novel case of an atypical Omenn syndrome (OS) phenotype due to mutations in the ADA gene encoding adenosine deaminase." (PMID 25954555, 2012). "Multiple genes presenting as Omenn syndrome, such as RAG1/2, ADA, LIG4, ZAP70, etc." (PMID 37755421, 2023). "SCID patients had disease-causing mutations in RAG1 or RAG2 (n = 4, two of them presented with Omenn syndrome), IL2RG (n = 4, one of them with confirmed maternal engraftment), NHEJ1 (n = 1), CD3E (n = 1), ADA (n = 1), JAK3 (n = 3, two of them with maternal engraftment) and DCLRE1C (n = 1)." (PMID 32265901, 2020). "Only 2 other patients with ADA-SCID and features of Omenn syndrome have been reported." (PMID 25954555, 2012).
pulmonary disease (7 papers, 2010 to 2025). "ADA-deficient patients frequently suffer from lung disease while ADA–/– mice develop rapid respiratory failure." (PMID 30918508, 2019). "Together, these studies demonstrate adenosine dependent expression of IL-6 during chronic stages of pulmonary disease in the ADA-deficient model." (PMID 21799929, 2011). "Moreover, deficiency in adenosine deaminase resulting in increased pulmonary adenosine levels actually leads to a fibrotic lung disease." (PMID 26369416, 2015). "Moreover, by 14 days post-partum (pp) ADA–/– mice develop alveolar proteinosis, leading to severe lung disease, hypoxia, and ultimate death by 3 weeks of age." (PMID 30918508, 2019). "In extra-pulmonary disease, tubercular samples 99/111 had ADA levels above the cutoff, while in non-tubercular samples 141/147 had below the cutoff level." (PMID 21629524, 2010). "In extra-pulmonary disease, tubercular samples 33/36 of ascitic fluid, 18/21 of synovial fluid and 48/54 of CSF had ADA levels above the cutoff, while in non-tubercular samples 72/72 of ascitic fluid, 6/9 of synovial fluid and 63/66 of CSF had values below the cutoff." (PMID 21629524, 2010).
AIDS (6 papers, 2007 to 2025). A syndrome resulting from the acquired deficiency of cellular immunity caused by the human immunodeficiency virus (HIV). "ADA activity has been found altered in various pathological conditions including acquired immunodeficiency syndrome (AIDS), anemia, lymphomas, tuberculosis, and leukemia." (PMID 30159340, 2018). "Moreover, ADA activity changes in a variety of other diseases including acquired immunodeficiency syndrome (AIDS), anemia, various lymphomas, tuberculosis, and leukemia." (PMID 24887139, 2014). "We conclude from our results that loss of ecto-ADA on CD8+ T cells may reflect a more senescent and dysfunctional phenotype, and that HIV-infected persons with low ADA expression on their CD8+ T cells may undergo a more rapid progression to AIDS." (PMID 23717651, 2013).
amyotrophic lateral sclerosis (6 papers, 2009 to 2026). Amyotrophic lateral sclerosis (ALS) is a neurodegenerative disease characterized by progressive muscular paralysis reflecting degeneration of motor neurons in the primary motor cortex, corticospinal tracts, brainstem and spinal cord. "Recent studies suggest that impairment in ADA regulation or isoenzyme distribution is associated with neurodegenerative diseases such as amyotrophic lateral sclerosis (ALS) and multiple sclerosis, although the mechanism leading to neurodegeneration is not clear at the moment." (PMID 37512494, 2023). "The role of adenosine deaminase RNA editing of glutamate and serotonin receptor transcripts is further exemplified by the disorder, amyotrophic lateral sclerosis (ALS) (MIM 105400)." (PMID 23675283, 2013). "Interestingly, however, in adenosine deaminase acting on RNA 2 (ADR2) knockout mice, a model of amyotrophic lateral sclerosis (ALS), motor neurons also show nuclear vacuoles." (PMID 39005321, 2024).
anemia (6 papers, 2015 to 2024). A reduction in the number of red blood cells, the amount of hemoglobin, and/or the volume of packed red blood cells. "Other findings included anemia, hyponatremia, substantially increased lactate dehydrogenase, and adenosine deaminase (ADA), consistent with tubercular or chronic infection." (PMID 39139350, 2024). "Despite being siblings, having severe anemia since infancy, markedly reduced bone marrow erythropoiesis and normal erythrocyte adenosine deaminase (eADA) activity levels, these patients had otherwise variable clinical phenotypes and outcome." (PMID 31839986, 2019). "In humans, DBA is often diagnosed during the first year of life; common clinical features include anemia, low reticulocyte count, macrocytic erythrocytes (see Box 1 for a glossary of terms), increased expression of fetal hemoglobin and elevated activity of adenosine deaminase (ADA)." (PMID 26398160, 2015).
DiGeorge syndrome (6 papers, 2014 to 2023). "The introduction of combined TREC and KREC tests can significantly advance early diagnosis of inborn errors of immunity, such as agammaglobulinemia, Nijmegen breakage syndrome, ataxia-teleangiectasia or DiGeorge syndrome, as well as late-onset ADA SCID." (PMID 33178177, 2020).
endothelial dysfunction (6 papers, 2018 to 2025). In vascular diseases, endothelial dysfunction is a systemic pathological state of the endothelium (the inner lining of blood vessels) and can be broadly defined as an imbalance between vasodilating and vasoconstricting substances produced by (or acting on) the endothelium. "The association between ADA and microvascular complications may be explained by the enzyme's role in modulating immune responses and promoting inflammatory pathways that contribute to endothelial dysfunction, a key factor in developing diabetic complications." (PMID 39493017, 2024). "We saw as well a significant reduction in the levels of ADA from baseline to post‐intervention, which is in line with the significant evidence of adenosine being involved in vascular barrier dysfunctions and endothelial dysfunction." (PMID 36467791, 2022). "OSM, MCP‐2, TGF‐α, and CXCL6 are likely to have an association with endothelial dysfunction and some are mostly or additionally involved in IR (MCP‐1, FGF‐21, TRAIL, and ADA) or insulin metabolism (TNFSF14/LIGHT)." (PMID 36467791, 2022). "The endothelial adenosine deaminase activity rapidly increased upon the stimulation by 4T1 cells and preceded cancer‐induced endothelial dysfunction." (PMID 30291675, 2018).
eosinophilia (6 papers, 2016 to 2025). "Moreover, ZAP70 deficiency, autoimmune lymphoproliferative syndrome (ALPS), selective IgA deficiency, and adenosine deaminase (ADA) deficiency have also appeared in differential diagnosis of eosinophilia." (PMID 27222657, 2016). "Notably, CNV analysis in two NDD children revealed mutated regions encompassing the ADA gene, associated with both ASD and eosinophilia, and the LAT gene, crucial for brain development and amino acid transport regulation." (PMID 41346380, 2025). "Among SCID, atopy and eosinophilia are frequently reported in Adenosine deaminase (ADA)-SCID." (PMID 33717395, 2021).
epilepsy (6 papers, 2009 to 2025). A brain disorder characterized by episodes of abnormally increased neuronal discharge resulting in transient episodes of sensory or motor neurological dysfunction, or psychic dysfunction. "Perampanel is an effective treatment for epilepsy with double-stranded RNA-specific adenosine deaminase deficiency." (PMID 40217360, 2025). "The adenosine deaminase ADAR2 is the main enzyme responsible for recoding editing and loss of ADAR2 function in mice leads to a phenotype of epilepsy and premature death." (PMID 19156214, 2009). "Fourteen epilepsy-associated genes were identified as potential targets of ADORA2A in epilepsy, and four key genes including NT5E, ENTPD1, ADA, and ADK were mainly involved in the “negative regulation of neuron death” and “purine nucleoside biosynthetic process” biological processes." (PMID 33262686, 2020). "ADA and ADK, identified as key target genes of ADORA2A on epilepsy, are involved in glioma progression, and their upregulated expression in peritumoral tissues is associated with epilepsy in glioma patients." (PMID 33262686, 2020). "In this review, we describe the contribution of 5’-nucleotidases, ADK, ADA, AMPD and nucleoside transporters in epilepsy, cognition, and neurodegenerative diseases with a particular attention on serious pathological conditions such as ALS and HD." (PMID 34054547, 2021). "Therefore, it appears that increased ADA and ADK may reduce adenosine levels, decrease its inhibitory activity and lead to epileptogenesis and progression of epilepsy in glioma patients." (PMID 30441833, 2018). "ADA and ADK expression was upregulated in peritumoral tissues derived from patients with epilepsy compared to those without epilepsy, whereas the number of ADA-positive or ADK-positive cells in tumor tissues was similar between glioma patients with and without epilepsy." (PMID 30441833, 2018).
infectious mononucleosis (6 papers, 2012 to 2024). A condition characterized by an increase in mononuclear white blood cells and swollen lymph nodes, which is usually caused by infection with the Epstein-Barr virus. "Furthermore, multivariate regression analysis revealed that adenosine deaminase level was a risk factor for elevated alanine transaminase in children with infectious mononucleosis." (PMID 35189820, 2022). "The adenosine deaminase level in the infectious mononucleosis group was significantly higher than that in the control group (P < 0.001)." (PMID 35189820, 2022). "The sensitivity and specificity of adenosine deaminase in predicting children with infectious mononucleosis were 97.1% and 94.0%, respectively." (PMID 35189820, 2022). "Adenosine deaminase may be a marker of the severity of infectious mononucleosis in children, and a predictor of elevated alanine transaminase in children with infectious mononucleosis." (PMID 35189820, 2022). "This study aimed to determine whether adenosine deaminase is a marker of severity in children with infectious mononucleosis, especially those with elevated alanine transaminase levels." (PMID 35189820, 2022). "Furthermore, the ADA levels among EBV-related diseases significantly differed, including infectious mononucleosis, atypical EBV infection, respiratory infection, malignant disease, and other diseases (P < 0.05)." (PMID 35986367, 2022).
melanoma (6 papers, 2010 to 2024). A malignant, usually aggressive tumor composed of atypical, neoplastic melanocytes. "The main clinical indications included acute lymphoblastic leukaemia, Parkinson's disease, haemophilia, defects of the bladder, knee cartilage lesions, adenosine deaminase deficiency, melanoma, stroke, multiple sclerosis and retinal disease." (PMID 32154598, 2021). "We show here that the intratumoral level of ADAR, the gene that encodes adenosine deaminase specific for dsRNA, the major A-to-I editing enzyme, also positively correlates with the AEI and negatively correlates with survival time in melanoma." (PMID 37691856, 2023). "All normal skin samples, as well as nevi and a couple of primary melanomas have relatively low values of ADA but they express TP63." (PMID 20805891, 2010). "There is a change of roles in metastatic and some primary melanomas, which have reduced TP63 expression but increased values of expression of ADA." (PMID 20805891, 2010).
multiple sclerosis (6 papers, 2017 to 2024). A progressive autoimmune disorder affecting the central nervous system resulting in demyelination. "The ADA genetic variant was further found to be associated with central inflammation and clinical presentations in multiple sclerosis." (PMID 36189232, 2022). "We determined that gender plays a role in ADA immunogenicity, a role undetected by the classical logrank-type test but reported in other interferon-β cohorts treated for multiple sclerosis." (PMID 28665947, 2017).
non-Hodgkin lymphoma (6 papers, 2013 to 2026). Distinct from Hodgkin lymphoma both morphologically and biologically, non-Hodgkin lymphoma (NHL) is characterized by the absence of Reed-Sternberg cells, can occur at any age, and usually presents as a localized or generalized lymphadenopathy associated with fever and weight loss. "Fludarabine, against lymphoid malignancies, particularly CLL and low-grade non-Hodgkin lymphoma (NHL), is with an advantage of resistance to ADA deamination." (PMID 34277446, 2021).
pericarditis (6 papers, 2020 to 2025). An inflammatory process affecting the pericardium. "On the other hand, a "probable" diagnosis is made when there is evidence of TB elsewhere in the body in a patient with unexplained pericarditis, the presence of a lymphocytic pericardial fluid with elevated adenosine deaminase (ADA) levels, and/or a positive response to anti-TB treatment." (PMID 39544618, 2024). "A probable diagnosis of TBP is made when, together with pericarditis, there is evidence of MTB in other bodily sites, elevated ADA levels in pericardial fluid, and epidemiological and clinical characteristics indicative of TB or improvement after antitubercular treatment (ex juvantibus criterion)." (PMID 38392848, 2024).
Pleuritis (6 papers, 2008 to 2025). Inflammation of the pleura. "Before the start of treatment, plasma levels of ferritin were raised in 13% and 45%, CRP in 21% and 64%, and ADA in 70% and 60% of TB lymphadenitis and pleuritis cases respectively." (PMID 39623309, 2024). "We assessed the levels of ferritin, CRP, and ADA in unstimulated plasma of TB lymphadenitis and pleuritis patients at baseline and changes in their levels with anti-TB treatment to see their utility as biomarkers to monitor treatment response." (PMID 39623309, 2024). "Twelve (35%) of the patients had culture 'confirmed TB' pleuritis, whereas 16 patients (47%) were diagnosed as 'probable TB' pleuritis based on ADA ≥30 U/L and/or clinical symptoms." (PMID 18366633, 2008). "Consider that for TB pleuritis, individuals with positive results for Xpert and ADA but negative results for culture and smear would be classified as disease-positive by CRS1+ and CRS2+ but disease-negative by CRS3+ and CRS4+." (PMID 35706064, 2022).